IL10 (interleukin 10)
Diseases named in the same sentence as IL10 in open-access papers (continued):
Sharing a sentence is not in itself a finding about the gene and the disease.
kidney (continued). "Our previous findings of increased numbers of antigen induced IL-10 as well as IFN-γ-producing T cells in non-tolerant controls in comparison with HY peptide induced skin graft tolerant mice 24 are also consistent with this." (PMID 20213737, 2010). "In a cohort of 58 kidney transplant recipients, IL-10-producing Breg could lead to non-immunosuppressant for at least 1 year after transplantation." (PMID 40264774, 2025). "To determine if the effector T cell-derived IL-10 had any impact on the outcome of RSV infection, we examined the effect of blockade of the IL-10 receptor (IL-10R) by in vivo administration of a blocking anti-IL-10Rα (α-IL-10R) mAb on virus clearance, pulmonary function and lung inflammation." (PMID 21829368, 2011). "We found a significant negative correlation between IL-10 concentrations and FVC, a correlation that merits further investigation as it may point to a restrictive or preserved ratio lung dysfunction." (PMID 38251391, 2024).
metabolic disorders (43 papers, 2012 to 2025). "IL-10 and IL-1β are pleiotropic cytokines with multiple biological effects linked to metabolic disorders." (PMID 38674931, 2024). "This shows how Blimp-1 affects adipose tissue metabolism via IL-10 and participates in the equilibrium between pro- and anti-inflammatory responses in metabolic disease." (PMID 40002370, 2025). "The results showed that decreased metabolic disorder in recipient mice was accompanied by a significant elevation of Th2-type cytokines, including IL-4, IL-5, IL-6, IL-10, and IL-13." (PMID 38195424, 2024). "Changes in the levels of circulatory cytokines are often observed during AD and metabolic disease and higher levels of IL-10 were observed in the circulation of the Control mice compared to the Probiotic mice." (PMID 35685773, 2022). "Lack of reagents specific for depletion of Tr1-like cells led us to examine the impact of IL-10 signaling neutralization on metabolic disease severity in aging." (PMID 34099626, 2021). "Here we identified miR-17~92 family miRNAs as key positive regulators supporting IL-10 production in ATMs, raising possibilities for this family of miRNAs as potential therapeutic targets of inflammatory and metabolic disorders." (PMID 33150865, 2020). "Since indigo was observed to be a strong inducer of IL-10 and its documented effect as a potent AhR ligand with the potential to impact metabolic disease, we identified indigo as our target of interest for this study." (PMID 30944419, 2019). "In fact, a number of systematic reviews have shown the association between inflammatory biomarkers, such as CRP, IL-1β, IL-6, TNF-α, IL-4, or IL-10, and cardio-metabolic diseases." (PMID 27527152, 2016). "In addition to the relationships with metabolic diseases, excessive fat accumulation can generate inflammatory responses by releasing IL-6 into the circulation, while it releases IL-10 as an anti-inflammatory strategy." (PMID 38792922, 2024). "Research suggests that moderate alcohol consumption may have an anti-inflammatory effect, by increasing the level of interleukin IL-10 and weakening the inflammatory response of monocytes; it may also be protective in relation to metabolic disorders and CVDs." (PMID 35565893, 2022). "Strategies aimed to overcome IL10 resistance, including SHIP1 agonists, might therefore hold therapeutic potential for reducing inflammation associated with metabolic disease." (PMID 26883847, 2016). "Stimulation of the macrophage cell line RAW264.7 with OSMR results increases the expression of M2 markers (IL-10, Arg1, and CD206), and the loss of OSMR leads to the polarization of adipose tissue macrophages to M1 phenotypes that increase inflammation in a mouse model of metabolic diseases." (PMID 37120549, 2023). "Additionally, the improvement of the intestinal barrier function plays an important role in attenuating metabolic diseases, with upregulating claudin 1, GLP1, IL-10, occludin 1, and ZO-1 expressions." (PMID 34579087, 2021). "Four plant derivatives, perillaldehyde, wogonoside, cinnamaldehyde, and 6-shogaol reduced levels of TNFα without decreasing IL-10, marking these compounds as potential immunomodulatory therapeutics for metabolic disease." (PMID 30944419, 2019). "In summary, PPSP could alleviate metabolic diseases by improving intestinal barrier function with upregulating GLUT4, GPR43, NLCR3, p38 MAPK, TRAF6-mediated signaling pathways and the expressions of claudin 1, GLP1, IL-10, occludin 1, and ZO-1." (PMID 34579087, 2021).
neurodegenerative disease (37 papers, 2012 to 2025). A disorder of the central nervous system characterized by gradual and progressive loss of neural tissue and neurologic function. "Given the central role of IL-10 in the pathophysiology of MS and other neurodegenerative diseases, its lower production in humans is considered a risk factor for MS." (PMID 40244087, 2025). "Impairments in IL10 production and signaling have also been implicated in neurodegenerative diseases including PD." (PMID 38741190, 2024). "While IL-10 is primarily recognized for its immunosuppressive properties, it has also been implicated in neuro–inflammation and neuro–degenerative diseases." (PMID 37759873, 2023). "Therefore, the precise role and its underlying mechanism of IL-10 in neurodegenerative diseases, including PD, needs further investigation." (PMID 31940754, 2020). "IL-10 overexpression was found to be beneficial for the treatment of several neurodegenerative diseases—including SCI, EAE, and AD —by reducing the expression of proinflammatory mediators and improving neurological functions." (PMID 36558562, 2022). "According to these studies, it was found that the role of IL-10 is changeable in different conditions of neurodegenerative diseases." (PMID 35432810, 2021). "Both up or downregulation of IL-10 cytokine will result in serious immunologic disorders, including neurodegenerative diseases." (PMID 33672866, 2021). "IL-10 administration seems to have a beneficial effect in most of the neurodegenerative diseases analyzed in this narrative review." (PMID 32659950, 2020). "The complex effect of IL-10 on innate immune activation status in the brain and proteostasis and neurodegenerative diseases indicates controlling the right dose of IL-10 under right condition is critical for brain development and function." (PMID 32611425, 2020). "The complex effect of IL-10 on innate immune activation status in the brain, proteostasis, and neurodegenerative diseases indicates controlling the right dose of IL-10 in the right condition is critical for brain development and function." (PMID 32611425, 2020). "Meanwhile, the decreased level of IL-10 has been reported to contribute to the neuroinflammatory process, which favors the development of neurodegenerative diseases including AD." (PMID 32230861, 2020). "Although it is difficult to identify the cellular sources of IL-10 in vivo, several neurodegenerative diseases and animal models of disease have reported the presence of IL-10 in CNS." (PMID 32532251, 2020). "Most of the supporting studies for IL-10-based therapies in neurodegenerative diseases have been conducted in animals." (PMID 32659950, 2020). "ASCs have been reported to have regenerative and immunosuppressive effects, mediated by the release of anti-inflammatory cytokines, such as IL-10, in pathological conditions like neurodegenerative diseases." (PMID 33101421, 2020). "The ability of IL-10 to decrease the production of pro-inflammatory cytokines has been suggested as a potential protective role in neurodegenerative diseases." (PMID 22363497, 2012). "Additionally, diltiazem has been shown to exert anti-inflammatory effects by modulating cytokine production, including IL-10 and IL-6, further supporting its potential role in neurodegenerative disease management." (PMID 41322300, 2025). "In both study groups, significant differences in common effect were observed for the anti-inflammatory cytokine IL-10, which could suggest a protective effect of this cytokine in patients with neurodegenerative diseases." (PMID 39751856, 2024). "Among the hub genes, IL-10 hub genes may help to discover targeted therapies for neurodegenerative disease because IL10 reduces TNF-α production in PD and increases Brain-derived neurotrophic factor (BDNF) levels." (PMID 39432502, 2024).
neurodegenerative disease (continued). "Here, we present a narrative review on the role of IL-10 in promoting the resolution of inflammatory cascades that are important for the brain integrity, focusing on the possible usefulness of IL-10 as a therapeutic or potential biomarker during neurodegenerative diseases." (PMID 32659950, 2020). "Neonatal BCG vaccination has been shown to induce on the one hand anti-inflammatory meningeal macrophage M2 polarization and neurotrophic factor expression that were T lymphocytes and Il-10 dependent and on the other hand neuroprotective Tregs in models of neurodegenerative diseases." (PMID 31697701, 2019). "In addition, we evaluated the effects of platycodigenin on the LPS-induced production of TNF-α, IL-6, IL-1β, and IL-10, which are important in neuroinflammation and neurodegenerative diseases." (PMID 31487775, 2019). "Therefore, the induction of IL10 release might be beneficial in several neurodegenerative diseases, where inflammation is harmful." (PMID 36231069, 2022). "In order to further explore the role of IL-10 in PD, large sample, multicenter, randomized controlled cohorts with comprehensive genetic and clinical analyses were needed to evaluate the therapeutic potential of IL-10 in neuroimmune and neurodegenerative disease." (PMID 30631418, 2018).
neurological disorders (34 papers, 2011 to 2025). "Although multiple cytokines (IL-4, IL-10, etc.)together inhibited neuroinflammation in neurological disorders, their functions were significantly different." (PMID 40134421, 2025). "Several strategies have also been developed for enhancing IL-10 levels in the context of neurological diseases using immune components." (PMID 38093354, 2023). "It is worth noting that besides its established role in regulating immune interactions in the CNS, numerous studies directly link impaired IL-10 production or signaling to neurological disorders in patients and animal models." (PMID 38179300, 2023). "M2 phenotype microglia play an important role in phagocytosis and removal of toxic substances in neurological diseases Both clinical and animal experiments have shown that IL‐10 expression levels increase in blood and brain tissue after ICH." (PMID 37614117, 2023). "Specifically, we highlight the potential importance of two cytokines, Ifng and Il10, in the development of flavivirus-induced neurologic disease." (PMID 35632766, 2022). "Our results highlight the preponderant role, at the expression level, of IL-17 and regulatory markers IL-4, IL-10, and Foxp3 in the blood as the major contributors to the segregation of the two studied neurological disorders." (PMID 33719347, 2021). "Particular differences in these networks included the finding that IL-8 exclusively modulated several molecules in the network constructed for neurological disease and exhibited an exclusive positive correlation with IL-10 and GM-CSF." (PMID 33776990, 2021). "The ratio of serum concentrations of Th1: Th2 cytokines, represented by IFNγ:IL-10, increased sequentially with disease duration in PD and was higher than of other neurological disorders and healthy controls." (PMID 30954070, 2019). "Strikingly, these data also show that fatal neurological disease in IL-10 KO mice is dependent on intravascular coagulation, as it can be prevented by LMWH treatment." (PMID 29866139, 2018). "The vascular endothelium is closely tied to the pathophysiology of these neurological disorders and research has demonstrated clear vascular endothelial protective properties for IL-10." (PMID 28659854, 2017). "Taking all this together, a variety of methods to increase IL-10 and test its therapeutic potential in neurological disorders with an immune component have been developed." (PMID 27881137, 2016). "It has been shown that DENV-2 induced IL-6, IFN-γ, and IL-10, and quercetin, naringin, catechin, and fisetin can change signaling pathways in the innate response to reduce neurological disorders being hopeful candidates for therapy of neurological disorders." (PMID 34764869, 2021). "IL-10 has become a potential therapeutic target for several neurological disorders." (PMID 33083463, 2020). "Serum levels of interleukin-10 (IL-10) and transforming growth factor-β1 are markedly elevated in new-onset NMOSD when compared with other neurological disorders." (PMID 40701519, 2025). "On the contrary, neurological presentations were inversely associated with markers of disease severity such as IL-6, TNF-α, IL-10/CXCL10, CRP, D-dimer, and LDH, all of which were significantly lower in patients with neurological diseases." (PMID 36851766, 2023). "COX-2, increased IL-10 and TGF-β1 in the brain tissue of rats and reduced plasma cytokines TNF-α, IL-1β, IL-2, IL-3, IL-4, IL-5, IL-6, etc. and exotoxin activity in plasma of different neurological disorders." (PMID 40297338, 2025). "This theory is supported by significantly elevated levels of serum cytokines IL‐6, TNF‐alpha, and IL‐10 in patients with IAE compared to those with no neurological disorders or not infected with influenza virus." (PMID 33155427, 2021).
intestinal disease (31 papers, 2011 to 2025). "In support of this hypothesis, intestinal disease in IL-10-deficient mice can be exacerbated by intentional infection with Helicobacter species that are commonly found in mouse colonies." (PMID 21994779, 2011). "In contrast, IL-10:KO mice on C57BL/6J background developed only mild intestinal disease with delayed onset." (PMID 40671790, 2025). "IBD patients that have mutations in the IL10 or IL10R genes suffer from very severe intestinal disease which indeed highlights that Tr1-mediated IL-10 signaling maintains tolerance to commensal microbiota in the gut." (PMID 36389662, 2022). "When gnotobiotic IL-10−/− mice are monocolonized with H. hepaticus they fail to develop intestinal disease, implicating the role of the normal GM in disease pathogenesis." (PMID 28553262, 2017). "Differences in rodent animal facilities are a notorious variable exemplified by studies on the role of IL-10 in intestinal disease." (PMID 21994779, 2011). "In essence, the blockade of IL‐10 by JAKi, especially Tyk2 inhibition, may lead to a differential effect of therapy across SpA spectrum joint and intestinal disease." (PMID 40320905, 2025). "Additionally, neutralization of IFNγ reduced intestinal disease in IL-10-/-TCRβ/δ-/- and IL-10-/- mice." (PMID 34938670, 2021). "Hence, pathogenic C. coli but not commensal E. coli caused differential kinetics in fecal bleeding in IL-10−/− and TLR4−/− IL-10−/− mice, indicating that TLR4 was involved in mediating the pathogen-induced signs of intestinal disease." (PMID 33261211, 2020).
hematological malignancies (23 papers, 2012 to 2025). "As Treg dysregulation has been implicated in numerous diseases, future studies into how IL-10 signaling is dysregulated in the context of inflammation or hematological malignancy represent promising areas of investigation." (PMID 33208555, 2020). "IL–10 overexpression was found to be associated with worse 3-year OS in both solid tumors (OR = 3.38, 95% CI = 2.22 to 5.15, P < 0.0001) and hematological malignances (OR = 3.29, 95% CI = 2.28 to 4.74, P < 0.0001)." (PMID 26440936, 2015). "Subgroup analysis showed that IL–10 overexpression was associated with worse 5-year OS in hematological malignancies (OR = 3.59, 95% CI = 2.26 to 5.72, P < 0.0001), however the amount of 5-year OS data in solid tumors was not enough for meta-analysis." (PMID 26440936, 2015). "In the present study, 12 patients with high-risk/advance stage hematologic malignancies treated with TCD haplo-HSCT were infused with donor T cells anergized toward the host allo-Ags by IL-10." (PMID 24550909, 2014). "Here, we describe the positive outcome of TCD haplo-HSCT combined with IL-10-DLI cell therapy in four patients with high-risk/advanced stage hematologic malignancies." (PMID 24550909, 2014). "Cytokines have been studied more in depth in hematological malignancies; however, in these studies, a noted association has been made that higher levels of interleukin 10 (IL-10) were found in BAL of patients who also had IPA or worst outcomes in patients with persistently elevated IL-6 and IL-8." (PMID 30687264, 2018). "A previous study observed elevated levels of IL-6, IL-8, and IL-10 in newly diagnosed hematological malignancies accompanied by pulmonary bacterial infections." (PMID 37114211, 2023). "Simultaneous expression of IL-10, IL-8, and IL-6 is a decisive advantage in newly diagnosed hematological malignancies and pediatric patients." (PMID 36319826, 2022). "In summary, our data indicate that IL-6, IL-8, and IL-10 are abnormally elevated in patients with lung bacterial infections in adult hematological malignancies." (PMID 34925324, 2021). "IL-6, IL-8 and IL-10 are abnormally elevated in patients with lung bacterial infections in adult hematological malignancies." (PMID 34925324, 2021). "In view of other people’s research and our results, we believe that cytokines, especially IL-6, IL-8 and IL-10, should be tested in patients with hematological malignancies." (PMID 34925324, 2021). "Subgroup analysis showed that the correlation between serous IL–10 expression and outcome of patients with solid tumors and hematological malignancies are consistent." (PMID 26440936, 2015). "The similar result was also observed in hematological malignancies, high IL–10 level correlated with worse OS at 1 year (OR = 3.07, 95% CI = 1.85 to 5.08, P < 0.0001)." (PMID 26440936, 2015). "IL–10 showed a close correlation with poor prognosis of both solid tumors and hematological malignancies." (PMID 26440936, 2015). "IL–10 is a valuable biomarker for prognostic prediction and targeting IL–10 treatment options for both solid tumors and hematological malignancies." (PMID 26440936, 2015). "In a pilot study, 12 patients affected by high-risk/advanced stage hematologic malignancies and previously treated with multiple lines of chemotherapy, were transplanted with haplo-HSCT and received IL-10-DLI after myeloid engraftment (ALT-TEN trial)." (PMID 24550909, 2014). "Here, we describe the outcome of patients with high-risk/advanced stage hematologic malignancies, who received T-cell depleted (TCD) haploidentical-HSCT (haplo-HSCT) combined with donor T lymphocytes pretreated with IL-10 (ALT-TEN trial)." (PMID 24550909, 2014). "In a proof-of-concept clinical study, the ALT-TEN trial, twelve patients with hematological malignancies undergoing haplo-HSCT were given IL-10-anergized donor T cells (IL10-DLI) containing Tr1 cells to support immune reconstitution in the absence of severe GvHD." (PMID 34177953, 2021).